BRAF (B-Raf proto-oncogene, serine/threonine kinase)
Diseases named in the same sentence as BRAF in open-access papers (continued):
Sharing a sentence is not in itself a finding about the gene and the disease.
melanoma (continued). "Crucial pathway alterations contribute to bioenergetic profile dysregulation in human melanoma, including B-Raf proto-oncogene serine/threonine-protein kinase (BRAF) mutations, neuroblastoma RAS viral oncogene protein (NRAS) overexpression, or deletion of PTEN, among others." (PMID 34895222, 2021). "Overall, the frequency of RAS, BRAF or neurofibromin 1 (NF1) mutations resulting in the activation of the MAPK pathway seems to be lower in ALM than in other subtypes of melanoma, and other drivers such as KIT, PAK1 and SPRED1 may be more important." (PMID 32330367, 2021). "Besides targeted therapy with BRAF and MEK inhibitors in BRAF V600 mutated melanomas, immune checkpoint inhibitors have revolutionized the treatment of patients with advanced melanoma and other cancers." (PMID 33925968, 2021). "Approximately 50% of melanomas harbor activating BRAF mutations." (PMID 34064013, 2021). "In addition, preclinical data suggest that BRAF mutation increases radiation resistance in both anaplastic thyroid cancer and melanoma." (PMID 34537078, 2021). "Approximately 60% of all melanomas are associated with a constitutive activating BRAF mutation." (PMID 34063443, 2021). "Among the miRNAs whose isoforms are associated with BRAF mutations, let-7a-5p and let-7b-5p are well known important tumor suppressor miRNAs which are downregulated in melanoma and inhibit proliferation and migration of melanoma cells." (PMID 34698264, 2021). "Of note EZH2 was also shown as a mediator of treatment resistance in BRAF mutated melanoma." (PMID 34063443, 2021). "In addition, our model is driven by an activating mutation in BRAF, which is the most common genetic defect found in melanoma, occurring in about half the cases." (PMID 35008307, 2021). "Considering our findings, trametinib, which is already approved for BRAF-mutated melanoma, can greatly potentiate the induction of HLA-I protein expression and, thus, might be a candidate for further clinical study in HCC with the addition of an ICI." (PMID 34458148, 2021). "NeoCombi was a single-arm, open-label, single-center, phase II trial, which enrolled patients who were affected by stage IIIB/C, BRAF V600-mutated melanoma and receiving dabrafenib plus trametinib for 12 weeks of neoadjuvant therapy before surgery, followed by 40 weeks of adjuvant therapy." (PMID 34178657, 2021). "This increased sensitivity was also evident in the WM983B melanoma line, which has a BRAF mutation." (PMID 35187538, 2021). "A key oncogenic factor in melanoma is the mutation of the BRAF gene." (PMID 34122546, 2021). "The CheckMate 066 study excluded patients with BRAF-mutated melanoma, which might have contributed to the good response rate and survival time." (PMID 34115870, 2021). "In addition, the fact that omics identified various metabolic-related signaling pathways, all together, prompted us to examine the effect of Octpep-1 in various metabolic parameters in melanoma BRAF-mutated cells." (PMID 33672955, 2021). "Furthermore, LOXL3 maintains genomic stability in melanoma by association with oncogenic BRAF in melanogenesis and promotes sustained proliferation." (PMID 34360836, 2021). "In around half of all melanoma cases, a mutation in the BRAF (most often V600E) is detected." (PMID 34068679, 2021). "It has been proven to be effective in treating metastasis melanoma which is prone to BRAF mutation." (PMID 34712139, 2021). "In addition, it was recently observed that melanoma CIMP associated with an NRAS-mutant phenotype is more aggressive than melanoma CIMP associated with BRAF-mutant melanoma." (PMID 34944843, 2021).
melanoma (continued). "Moreover, low TYR expression in BRAF-mutated melanoma subtypes showed a significant association with longer survival." (PMID 34199192, 2021). "However, treatment of mice with Y-27632 following the injection of melanoma cells harboring a BRAF mutation promotes tumor growth." (PMID 34503171, 2021). "Thus, BRAF inhibitors are important chemotherapeutic treatments for unresectable or metastatic BRAF mutated melanoma." (PMID 34526609, 2021). "The frequency of BRAF V600E mutation was reported as high as 50%-80% in melanoma." (PMID 34094962, 2021). "Actually, in patients showing lymph nodes positivity, the presence of c-met and Nox-4 starts to increase in BRAF mutated cases, but becomes statistically relevant only in cases of distant metastasis, indicating Nox4 as a possible melanoma severity marker as well as c-met." (PMID 33451139, 2021). "Important clinical progress was achieved in adults with BCR-ABL fusion positive chronic myeloid leukemia, HER2-positive breast cancer, lung cancer harboring EGFR mutations or EML4-ALK translocations as well as BRAF-V600E mutated melanoma with BRAF and MEK inhibitors." (PMID 34503139, 2021). "The isobologram summarizes the combination index (CI) at the IC50 when the SMO inhibitor MRT-92 and the BRD4-degrader MZ1 were combined, showing a moderate synergistic anti-proliferative effect (CI < 1) in melanoma cells independently of their BRAF, NRAS, and NF1 mutational status." (PMID 33958721, 2021). "Indeed, BRAF mutations were reported in 50% cutaneous melanoma and 15% acral melanoma cases; the latter is the most common subtype in Chinese melanoma patients." (PMID 34504796, 2021). "Also, SIJ1777 substantially inhibits the activation of MEK, ERK, and AKT on melanoma cells harboring BRAF class I/II/III mutations." (PMID 33917428, 2021). "Characterized public neoantigens generally occur in genes that play an important role in facilitating tumourigenesis or driving continued tumour growth, for instance the gain-of function BRAF V600E mutation that confers a constitutive proliferative drive in melanoma." (PMID 34439399, 2021). "Recently, new reports tried to assess the existence of any correlation between mutations in the main genes (BRAF/NRAS) involved in melanoma initiation and progression; they have proposed a distinct molecular classification for MUP to explain the differences in patient outcomes." (PMID 33747946, 2021). "BRAF mutations occur frequently in up to 66% of patients with melanoma, while these activation mutations in BRAF lead to constitutive activation of kinase function independent of upstream signaling from RAS, ultimately promoting cell growth and inhibiting cell apoptosis." (PMID 34035810, 2021). "However, miR-129-5p expression was elevated in BRAF mutated melanoma patients harboring EZH2 missense or silencing mutations compared to wildtype EZH2." (PMID 34063443, 2021). "In 2013, dabrafenib was approved by the FDA for unresectable or metastatic BRAF-mutated melanoma." (PMID 34868763, 2021). "Notably AXL upregulation is associated with MITFlow state in NRAS- and BRAF-mutated melanomas leading to increased survival, therapy resistance and dormancy." (PMID 33870460, 2021). "Additionally, adjuvant use of BRAF/MEK inhibitors resulted in a lower risk of relapse in patients with stage III melanoma." (PMID 34304249, 2021). "Current studies investigate which therapy sequence is best for patients with BRAF mutated melanoma." (PMID 34944771, 2021). "Our data suggest that the regulation of the STAT pathway by RICTOR could, at least, mediate resistance in BRAF-mutated melanoma cells." (PMID 34680615, 2021). "Additionally, the correlation between histopathological subtypes of BRAF/NRAS-mutated melanoma and PLA1A was analyzed." (PMID 33723350, 2021). "It remains unclear why the same genetic mutation in the BRAF gene has such different consequences in moles and melanomas." (PMID 34812139, 2021).
melanoma (continued). "Similarly, the baseline mutant allele fraction and total level of ctDNA has been shown to be correlated with tumor burden in BRAF-mutated melanoma patients treated with combinational therapy including BRAF inhibitors." (PMID 33255267, 2020). "Indeed, 37 to 60% of melanomas, typically those related to intermittent sun exposure damage, show a somatic mutation in BRAF." (PMID 32695793, 2020). "Only one subungual melanoma had a BRAF mutation (toenail with p.V600E)." (PMID 33067454, 2020). "We posit that a DDR/collagen axis may contribute to the resistant phenotype of BRAF-mutated melanomas and therefore a rationale target to restore therapeutic efficacy." (PMID 33014862, 2020). "To investigate whether the expression of any validated BRAFi-resistant genes associated with BRAFi resistance in melanoma patients, we analyzed expression data from two independent cohorts treated with BRAF inhibitors." (PMID 32413516, 2020). "Indeed, using a mouse xenograft model, the authors observed that this mutation enhances melanoma growth and invasion and confers drug resistance against BRAF and MEK kinase inhibitors." (PMID 33072757, 2020). "The retrospective study design limits the interpretation of our results, the lack of a control arm, as well as the small size of patients’ subsets with a heterogeneous cohort, including BRAF-mutated and BRAF WT-melanomas treated with different combination therapies." (PMID 32585901, 2020). "BRAF V600 mutation has been found in 48-69% of patients with melanoma." (PMID 32775409, 2020). "Another study has established that MAPK pathway inhibition following BRAF inhibitor treatment induced rapid increases in MET and GAB1 expression and MET amplification was also observed to co-exist with BRAF hotspot mutations and represent the most common amplification among RTKs in melanomas." (PMID 32659961, 2020). "Thus, the natural mutation of the BRAF gene is a hotspot target for scientists to study resistance to melanoma, and the inhibitor of mutated BRAF enzyme Vemurafenib and Dabrafenib have been marketed successively." (PMID 33344444, 2020). "In a cellular model for acquired vemurafenib resistance in BRAF V600E mutated melanoma, Gupta and colleagues systematically identified epigenetic regulators mediating drug resistance using a short-hairpin library to downregulate more than 300 genes known to be involved in epigenetic control." (PMID 32046099, 2020). "Splicing variants of BRAF are found in approximately 13–30% of resistant melanomas." (PMID 32605090, 2020). "It seems that mutations in the NF1 gene co-occur with BRAF mutations in melanomas and may also play a role in acquiring resistance to BRAF inhibitors." (PMID 32605090, 2020). "Our work suggests that UV exposure may stimulate oncogenic mutations in BRAF and potentially other melanoma driver genes by inducing the formation of rare, but highly mutagenic, photoproducts." (PMID 33207206, 2020). "The evolution of melanoma, the most aggressive type of skin cancer, is triggered by driver mutations that are acquired in the coding regions of particularly BRAF (rat fibrosarcoma serine/threonine kinase, isoform B) or NRAS (neuroblastoma-type ras sarcoma virus) in melanocytes." (PMID 32878000, 2020). "In melanoma, the most prevalent oncogenic mutations are of course those in the BRAF gene." (PMID 32258034, 2020). "MAPK inhibitors, such as BRAF inhibitors (e.g., vemurafenib, dabrafenib, and encorafenib), MEK inhibitors (e.g., cobimetinib, trametinib, and binimetinib), or their combination, are beneficial for most melanoma patients with tumor carrying activating V600E/K mutation in the BRAF oncogene." (PMID 32708687, 2020). "Interestingly, we observed a significant difference in the load of V600E between the early and late melanoma stages, in the sense of an inverse correlation between BRAF V600E mutational load and melanoma progression." (PMID 32168325, 2020).
melanoma (continued). "The identification of BRAF mutations is crucial for personalized treatment of melanoma, being an important tool for diagnosis, treatment, predictor of patient outcomes, and may have an impact on prognosis." (PMID 32695793, 2020). "A first estimate of the percentage of BRAFi-unresponsive patients with BRAF-mutated melanoma came from the BRIM2 phase 2 clinical study, in which an impressive unresponsive rate of 47% to vemurafenib monotherapy was observed that was then confirmed by the phase-3 study." (PMID 33419275, 2020). "The genes with the most frequent mutations in melanoma are BRAF and NRAS." (PMID 32775409, 2020). "BRAF V600E positivity was significantly associated with thicker melanoma (p = 0.0015)." (PMID 32143442, 2020). "BRAF splicing variants are known to confer melanoma resistance to BRAF inhibitors." (PMID 33216826, 2020). "Mutations in the protooncogene BRAF constitute about half of melanoma cases worldwide." (PMID 32565808, 2020). "This was also observed in biopsies from melanoma patients harboring BRAF V600E mutations." (PMID 32046099, 2020). "Currently, only two non-specific AMPK activators, phenformin and metformin, that have been approved for treating type II diabetes are undergoing clinic evaluations as combinatorial agents for treating BRAF-mutated melanoma together with vemurafenib or dabrafenib/trametinib." (PMID 32807225, 2020). "Here, we lowered the oxygen concentration applied to melanoma cells to 1% and isolated EVs of four melanoma cell lines (two carrying the BRAF V600E mutation (A375, 501Mel) and two carrying an NRAS mutation (MelJuso, IPC298)); control cells were kept under normoxic conditions." (PMID 32183388, 2020). "Immunosuppressive mechanisms exhibited by BRAF V600E-mutated melanoma." (PMID 33171792, 2020). "Furthermore, other PI3K/Akt pathway mutations (such as PTEN, mTOR, PIK3R1, and NFKB1) can co-occur in melanoma with BRAF (17–20%) or NRAS (9%) mutations." (PMID 33081092, 2020). "BRAF p.V600K was detected in 15% of mutated melanoma samples." (PMID 32340363, 2020). "Neil Rosen’s group also clearly demonstrated that vemurafenib treatment of BRAF mutant melanoma cells caused receptor tyrosine kinase-mediated (RTK) activation of RAS via Spry2 downregulation, with CRAF activation and pERK rebound after initial profound inhibition." (PMID 32922659, 2020). "Indeed, BRAF is the most commonly mutated gene in melanoma, a deadly skin cancer that arises from melanocytes." (PMID 33047672, 2020). "Thus, thyroid carcinomas bearing BRAF mutations are less sensitive to BRAF inhibitors than melanomas and develop primary or acquired resistance due to additional mutations and activation of alternative signaling pathways that reinforce ERK signaling." (PMID 32111026, 2020). "The yeast reversion assays described in this study could be used to investigate whether other mutagens cause these recurrent BRAF mutations, essentially as a type of Ames test for the causes of oncogenic mutations found in melanoma and other cancers." (PMID 33207206, 2020). "The aim of this review is to describe the landscape of mutated non-BRAF melanoma, in light of recent data deriving from Next-Generation Sequencing (NGS) (or Massive Parallel Sequencing – MPS) analysis, focusing on available, or in experimentation, targeted therapies." (PMID 32850962, 2020). "Sixteen patients had BRAF-mutated melanomas, including BRAF p.V600E (n = 12) or p.V600K (n = 4)." (PMID 32731406, 2020). "In melanoma, 46% of the detected variants were found in BRAF and 15% in NRAS genes." (PMID 33083132, 2020). "Major advances have been made in the clinical management of melanoma patients carrying BRAF mutations with the adoption of two BRAF specific inhibitors, namely vemurafenib and dabrafenib, approved by the Food and Drug Administration (FDA) in 2011 and 2013, respectively." (PMID 32393282, 2020). "Missense mutations in the BRAF oncogene occur in more than 50% of malignant melanomas." (PMID 33292222, 2020).
melanoma (continued). "This conclusion is very interesting and suggests a possible relationship between melanoma and sarcoma, which may provide a new perspective for the study of BRAF mutations in sarcomas." (PMID 32476297, 2020). "Furthermore, NRP2, PLXNC1 and PLXNB3 were also positively associated with cell sensitivity to Dabrafenib, which is the treatment for late-stage melanoma and metastatic non-small cell lung cancer with BRAF V600E or V600K mutations." (PMID 32640719, 2020). "Improved survival with vemurafenib in melanoma with BRAF V600E mutation.." (PMID 32308931, 2020). "In melanoma, high levels of MDSCs are also associated with resistance to BRAF inhibitors." (PMID 33036192, 2020). "The BRAF V600E mutation is the most frequent driver mutation in melanoma." (PMID 33207206, 2020). "Furthermore, the BRAF V600E mutation has also been associated with a reduced survival in other types of tumors like melanoma or papillary thyroid cancer." (PMID 31952366, 2020). "Furthermore, melanoma tumors often develop drug resistance to BRAF (V600E) inhibitors by expressing a shorter isoform of mutated BRAF that lacks the RAS binding domain and allows BRAF (V600E) proteins to dimerize and signal in a RAS independent manner." (PMID 32879328, 2020). "BRAF/MEK inhibitor resistance in melanoma is associated with increased expression of EGFR." (PMID 32626712, 2020). "Researchers have found that nearly half of all melanoma patients have a mutated BRAF gene." (PMID 33344444, 2020). "Intriguingly, mutated BRAF cooperates with alterations in PTEN/AKT to promote melanoma progression." (PMID 32714859, 2020). "Dual MAPK pathway inhibition is a standard treatment option for BRAF-mutated melanoma." (PMID 32645969, 2020). "However, clinical inhibitors of RAC1 are not currently available although SRF/MRTF inhibitors in combination with BRAF inhibitors have been recently demonstrated to have utility in the treatment of BRAF mutant melanoma with an RAC1 P29S mutation." (PMID 32850962, 2020). "In specific cases, such as melanomas with BRAF mutations, the need for adjuvant radiotherapy may even be put into question." (PMID 32850007, 2020). "Treatment with BRAF inhibitors dabrafenib and vemurafenib can be associated with the abnormal skin growth, forming papilloma, keratoacanthoma, nevi, or even skin cancers such as squamous cell carcinoma and melanoma." (PMID 32751138, 2020). "As a result, a post-marketing surveillance (PMS) of dabrafenib and trametinib in Japanese patients with unresectable melanoma with BRAF mutation was initiated in June 2016 to determine the safety and efficacy of dabrafenib and trametinib in a Japanese clinical setting." (PMID 32699976, 2020). "We used three different cell lines with frequent gene mutations in melanoma (BRAF, NRAS, or cKIT)." (PMID 32455924, 2020). "Tumour T-cell infiltrates are reduced in BRAF-mutated melanomas." (PMID 32645969, 2020). "Mutations in the kinase domain of BRAF occur with a frequency around 50% in melanoma patients." (PMID 32054102, 2020). "To test our hypothesis, we focused on MITF and SOX10 as the two most essential TFs in skin and used the A375 melanoma cell line harbouring the BRAF activating mutation." (PMID 33073517, 2020). "Here we explore whether alternative BRAF splicing variants can be detected in melanoma patients who have developed resistance to BRAF inhibitor therapy." (PMID 33216826, 2020). "Approximately 40–60% of melanomas harbour an activating mutation in the BRAF oncogene." (PMID 32613561, 2020). "However, we observed a significant higher ST8SIA1 expression in melanoma patients with BRAF V600e mutation compared to those that were triple WT (wild type of BRAF, NRAS, and NF1 mutations) or NRAS mutation(s) alone." (PMID 32358995, 2020). "Roughly 50% of melanoma cases express a BRAF mutation (BRAF-MT) and may either be treated with a BRAF/MEK inhibitor combination or ICI therapy." (PMID 32545409, 2020).